ATP2B1 (ATPase plasma membrane Ca2+ transporting 1)
Description:
Catalyzes the hydrolysis of ATP coupled with the transport of calcium from the cytoplasm to the extracellular space thereby maintaining intracellular calcium homeostasis. Plays a role in blood pressure regulation through regulation of intracellular calcium concentration and nitric oxide production leading to regulation of vascular smooth muscle cells vasoconstriction. Positively regulates bone mineralization through absorption of calcium from the intestine. Plays dual roles in osteoclast differentiation and survival by regulating RANKL-induced calcium oscillations in preosteoclasts and mediating calcium extrusion in mature osteoclasts (By similarity). Regulates insulin sensitivity through calcium/calmodulin signaling pathway by regulating AKT1 activation and NOS3 activation in endothelial cells. May play a role in synaptic transmission by modulating calcium and proton dynamics at the synaptic vesicles.
Synonyms: PMCA1; MRD66; PMCA1kb
Tractability: Antibody: UniProt places it where antibodies can reach, with high confidence; its Gene Ontology location is reachable by antibodies, with high confidence; UniProt predicts a signal peptide or a membrane-spanning region; the Human Protein Atlas places it where antibodies can reach. PROTAC: ubiquitination databases record sites on it; its protein half-life has been measured.
Gene: Protein-coding gene on chromosome 12 (89,588,049 to 89,709,527, reverse strand). Ensembl gene ENSG00000070961.
Subcellular location: Cell membrane; Basolateral cell membrane; Synapse; Presynaptic cell membrane; Cytoplasmic vesicle, secretory vesicle, synaptic vesicle membrane
Subcellular location (Human Protein Atlas): Plasma membrane
Pathways (Reactome):
Hemostasis: Reduction of cytosolic Ca++ levels
Muscle contraction: Ion homeostasis
Sensory Perception: Sensory processing of sound by inner hair cells of the cochlea
Transport of small molecules: Ion transport by P-type ATPases
Gene Ontology:
Molecular function: ATP hydrolysis activity; calcium ion transmembrane transporter activity; protein binding; P-type calcium transporter activity; ATP binding; nucleotide binding
Biological process: calcium ion export across plasma membrane; negative regulation of cytosolic calcium ion concentration; regulation of cellular response to insulin stimulus; regulation of cytosolic calcium ion concentration; monoatomic ion transmembrane transport; negative regulation of cytokine production; positive regulation of bone mineralization; positive regulation of calcium ion transport; regulation of blood pressure; regulation of cardiac conduction; regulation of vascular associated smooth muscle contraction; calcium ion transmembrane transport; intracellular calcium ion homeostasis
Cellular component: extracellular exosome; membrane; plasma membrane; basolateral plasma membrane; immunological synapse; presynaptic membrane; synapse; synaptic vesicle membrane; glutamatergic synapse; photoreceptor ribbon synapse
Genetic constraint (gnomAD): Loss-of-function variants: 12 observed, 112.92 expected, observed/expected ratio (o/e) 0.11, 90% interval 0.067 to 0.17. The upper end of that interval is the gene's LOEUF score, 0.17, which puts it in group 1 of 6, group 1 being the genes least tolerant of losing a copy. Missense variants: 752 observed, 1,494.1 expected, observed/expected ratio (o/e) 0.5, 90% interval 0.47 to 0.54. Synonymous variants: 447 observed, 507.23 expected, observed/expected ratio (o/e) 0.88, 90% interval 0.81 to 0.95.
Homologues: Orthologues: chimpanzee ATP2B1 (100% identical), macaque ATP2B1 (100% identical), rabbit ATP2B1 (99% identical), mouse Atp2b1 (99% identical), dog ATP2B1 (99% identical), guinea pig ATP2B1 (99% identical), pig ATP2B1 (99% identical), rat Atp2b1 (98% identical), tropical clawed frog atp2b1 (90% identical), zebrafish atp2b1a (85% identical), zebrafish atp2b1b (81% identical), Drosophila melanogaster SPoCk (21% identical), and 8 more. Paralogues in human: ATP2B2 (80% identical), ATP2B3 (80% identical), ATP2B4 (76% identical), ATP2A2 (25% identical), ATP2A3 (25% identical), ATP2A1 (25% identical), ATP1A1 (24% identical), ATP1A2 (24% identical), ATP1A3 (24% identical), ATP12A (23% identical), ATP1A4 (23% identical), ATP2C1 (23% identical), and 9 more.
Diseases named in the same sentence as ATP2B1 in open-access papers:
ATP2B1 is named in the same sentence as 52 diseases in open-access papers, as found by Europe PMC text mining. Sharing a sentence is not in itself a finding about the gene and the disease. The quoted sentences say what the papers report.
Hypertension (28 papers, 2010 to 2026). The presence of chronic increased pressure in the systemic arterial system. "The PLCE1-rs932764-G and ATP2B1-rs17249754-G variants, known for their role in hypertension, were significantly associated with a decreasing risk of cardiomyopathy (p = 0.006 and 0.04, respectively)." (PMID 40413218, 2025). "For example, previous studies have reported an association between hypertension and ATP2B1 and ALDH2 gene variants." (PMID 39684400, 2024). "New association signals from cross-ancestry GWASs included, for example, variants at PROCR, GRK5 and F11 (thrombosis), LPA and ATP2B1 (lipid metabolism, hypertension and atherosclerosis), SWAP70 (membrane ruffling) and LAMC1 (cerebrovascular matrisome)." (PMID 36180795, 2022). "A higher risk of hypertension was demonstrated also with the single-nucleotide polymorphism of ATP2B1 (ATPase Plasma Membrane Ca2+ Transporting 1)." (PMID 35624760, 2022). "The current study suggests that ATP2B1 became a susceptibility gene for hypertension via natural selection of this SNP." (PMID 33777100, 2021). "Based on the GWASs and the following replication studies, the SNP rs2681472 of the ATP2B1 gene was confirmed to be associated with blood pressure or hypertension in various populations." (PMID 33777100, 2021). "ATP2B1 is a well-established hypertension and blood pressure locus, where the same alleles increase the risk for FMD and hypertension." (PMID 34654805, 2021). "The association of ATP2B1 with hypertension has been shown in numerous studies across different ethnic groups; to date, there are at least six different SNPs within ATP2B1 which are associated with elevated blood pressure." (PMID 33013458, 2020). "The association of ATP2B1 rs11105378 with hypertension was reported in European, Japanese and Korean studies." (PMID 32854392, 2020). "In contrast to GWAS data for ATP2B4, SNPs located in ATP2B1, the gene encoding PMCA1, have been strongly associated with CVDs, including hypertension, coronary artery disease and MI." (PMID 33013458, 2020). "Interaction of BMI, gender and ATP2B1 rs17249754 in susceptibility to hypertension has been also reported in Han Chinese Population." (PMID 31242870, 2019). "Concerning ATP2B1 rs2681472, it was found to be associated with hypertension firstly in 2009 by Levy and al.." (PMID 31242870, 2019). "Recently STK39 rs3754777, ATP2B1 rs2681472 and rs17249754 have been associated with BP variation and hypertension." (PMID 31242870, 2019). "The results of association between ATP2B1 and hypertension were similar to those from previous studies." (PMID 28273873, 2017). "It is interesting to note that one of these hypertension-related trans-eGenes, ATP2B1, is also a cis-eGene of the lead CAD/MI GWAS risk SNP at the ATP2B1 locus." (PMID 28122634, 2017). "Plasma membrane calcium pump isoform 1 (PMCA1) is encoded by ATPase plasma membrane Ca2+transporting 1 (ATP2B1), the most likely candidate gene responsible for hypertension." (PMID 28611155, 2017). "In conclusion, two genetic variants in PLCE1 and ATP2B1 are inversely associated with hypertension and cardiotoxicity susceptibility." (PMID 28851949, 2017). "Crossover analysis and stratified analysis indicated that BMI has a major effect on the development of hypertension, while ATP2B1 variants have a minor effect." (PMID 26933664, 2016). "In the present study, MDR analysis demonstrated that BMI itself and the interaction between ATP2B1 variants and BMI increase the susceptibility to hypertension." (PMID 26933664, 2016). "To determine the manner in which BMI and ATP2B1 variants interact to cause hypertension, we performed a stratified analysis." (PMID 26933664, 2016). "Because BMI represents the internal metabolic status and physiological environment, it is not surprising that BMI has a major effect in the development of hypertension, while the ATP2B1 variants have a minor effect." (PMID 26933664, 2016).
Hypertension (continued). "Previous genome-wide association studies (GWASs) found that several ATP2B1 variants are associated with essential hypertension (EHT)." (PMID 26933664, 2016). "The genomic region containing the ATP2B1 gene was previously identified in a genome-wide association study of blood pressure and hypertension." (PMID 20700443, 2010). "Interestingly, genome-wide association studies have associated the ATP2B1 gene, encoding PMCA1, with hypertension." (PMID 39392480, 2024). "Notably, four loci, rs11899121 (chr2p24), rs7556898 (chr2q24.3), rs17249754 (ATP2B1), and rs1980854 (chr20p12.2), were significantly associated with hypertension in the high-METS-score group (T3)." (PMID 39684400, 2024). "The association of ATP2B1 rs17249754 with hypertension has been previously shown in Koreans." (PMID 31242870, 2019). "In addition to PLCE1, carriers of the hypertension risk allele in ATP2B1 were at a reduced risk of cardiotoxicity." (PMID 28851949, 2017). "Similarly, the association between ATP2B1:rs17249754 and cardiotoxicity risk was protective with carriers of at least one of the hypertension risk alleles having an approximately 74% reduction in risk of cardiotoxicity (95% CI: 0.07–96, P = 0.040)." (PMID 28851949, 2017). "The results of this study suggest that Atp2b1 may be an important risk factor for the development and progression of hypertension." (PMID 28795531, 2017). "A recent meta-analysis study showed that the group of risk alleles, which were the same as the wild type ATP2B1 rs17249754, was significantly and positively associated with the increase of blood pressure and hypertension (β = 0.15 p-value = 1.75 × 10−11 with hypertension)." (PMID 28273873, 2017). "Moreover, the interaction of BMI and ATP2B1 variants increased the susceptibility to hypertension, with BMI having a major effect and ATP2B1 variants having a minor effect." (PMID 26933664, 2016). "However, when BMI <25, the A allele of rs2070759 or the G allele of rs17249754 showed a significant association with hypertension, indicating that BMI has a major effect and that the ATP2B1 variants have minor effects." (PMID 26933664, 2016). "Similar findings in different ethnic groups further strengthen the hypothesis that the ATP2B1 gene is a susceptibility locus of likely global significance for BP variation and the development of hypertension." (PMID 26933664, 2016). "Notably, four loci (rs11899121 [chr2p24], rs7556898 [chr2q24.3], rs17249754 [ATP2B1], and rs1980854 [chr20p12.2]) were significantly associated with hypertension in the high-METS-IR group (T3), rs10857147 (FGF5) was significant in both T1 and T3, and rs671 (ALDH2) was significant only in T1." (PMID 39684400, 2024). "However, a Korean genome epidemiology study showed that ATP2B1 rs17249754 polymorphism may be increased the incident hypertension, when sodium was excessively consumed." (PMID 34722659, 2021). "Thus, the pathways implicated in hypertension at the SH2B3 locus may intersect with pathways at the ATP2B1 locus." (PMID 28122634, 2017). "This inverse relationship between PLCE1:rs932764 and ATP2B1:rs17249754 associations with hypertension and cardiotoxicity suggests that the biological function of these two genes are different in the setting of hypertension verses response to anthracyclines resulting in cardiotoxicity." (PMID 28851949, 2017). "Moreover, in a study by the Japanese Millennium Genome Project, another ATP2B1 variant, rs11105378, was found to have the most significant association with hypertension (P = 4.1 × 10−11), and the association was cross-validated by replication analysis with the Global BPgen dataset (P = 5.9 × 10−4)." (PMID 26933664, 2016). "Among these, three markers, rs11899121 on chromosome 2p24, rs7556898 on chromosome 2q24.3, and rs17249754 in the ATP2B1 gene, lowered the prevalence of hypertension in individuals with a high METS-IR." (PMID 39684400, 2024).
Hypertension (continued). "Homozygous Atp2b1 knockout (ko) mouse is embryonically lethal before organogenesis, whereas heterozygous Atp2b1-ko mice have hypertension, hypocalcemia with decreased intact parathyroid hormone (PTH) levels, and increased bone mineral density." (PMID 37926713, 2024). "Meanwhile, GMDR analysis showed no statistical difference between the interaction of CYP17A1 and ATP2B1 on hypertension." (PMID 34722659, 2021). "After dozens of GWASs on hypertension, ATP2B1 is the first gene to have been cross-validated in different GWASs." (PMID 33777100, 2021). "GWASs have confirmed that the ATP2B1 encoding plasma membrane Ca2+ ATPase 1 (PMCA1) is strongly associated with BP and hypertension." (PMID 34722659, 2021). "In this cross-sectional study of hypertensive molecular epidemiology, the association of the ATP2B1 and CYP17A1 SNPs, and their haplotypes, G × G and G × E interactions, with hypertension in the Maonan population was observed for the first time." (PMID 34722659, 2021). "Genomewide association studies have linked ATP2B1, the gene for the plasma membrane calcium ATPase 1 (PMCA1), to blood pressure (BP) and hypertension." (PMID 28795531, 2017). "Furthermore, heterozygous deletion of ATP2B1 proved that decreased PMCA1 activity promoted vascular remodeling in mice, which then developed hypertension at higher age." (PMID 39392480, 2024). "Therefore, the purpose of this research was to test the association of ATP2B1 (rs1401982 and rs17249754) and CYP17A1 (rs1004467 and rs11191548) SNPs, and their haplotypes, G × G and G × E interactions, with hypertension in the Maonan population." (PMID 34722659, 2021). "In 2009, a GWAS conducted by the Cohorts for Heart and Aging Research in Genome Epidemiology (CHARGE) consortium found that ATP2B1 genetic polymorphisms were significantly related to systolic blood pressure (SBP), diastolic blood pressure (DBP), and hypertension." (PMID 33777100, 2021). "However, the evidence that showed the relationship of ATP2B1 and CYP17A1 with the hypertension risk from Maonan being one of China's ethnic minorities was still rare." (PMID 34722659, 2021). "Moreover, combined analysis of the two largest cohorts, CHARGE and Global BPgen, further confirmed that only ATP2B1 variants were able to reach genome-wide significance (P < 5 × 10−8) with SBP (rs2681492), DBP (rs2681472) and hypertension (rs2681472)." (PMID 33777100, 2021). "Meanwhile, the haplotypes of CYP17A1 rs1004467A-rs11191548T, CYP17A1 rs1004467G-rs11191548C, and ATP2B1 rs1401982G-rs17249754A had a protective effect for hypertension, whereas the haplotype of ATP2B1 rs1401982A-rs17249754G revealed an increased susceptibility of disease (p < 0.001)." (PMID 34722659, 2021). "Recently, with the enormous progress made in molecular Biology domain, Genome-wide association studies (GWAS) have identified news genes and their variants which are associated with blood pressure variations and the risk of hypertension such as STK39 rs3754777, ATP2B1 rs2681472 and rs17249754." (PMID 31242870, 2019). "Hypertension-susceptibility alleles of PLCE1:rs9327264 and ATP2B1:rs17249754 were significantly associated with cardiotoxicity risk conferring a protective effect with a 64% (95% CI: 0.18–0.76, P = 0.0068) and 74% (95% CI: 0.07–0.96, P = 0.040) reduction in risk, respectively." (PMID 28851949, 2017). "In this study, two established hypertension-susceptibility alleles identified in the general population (PLCE1:rs932764 and ATP2B1:rs17249754) were also identified as predictors of cardiotoxicity risk in long-term childhood cancer survivors exposed to anthracyclines." (PMID 28851949, 2017). "Our findings demonstrate that the hypertension-susceptibility variants in PLCE1 and ATP2B1 confer a protective effect on risk of developing anthracycline-related cardiotoxicity, and functional analyses suggest that these genes are influenced by exposure to anthracyclines." (PMID 28851949, 2017).
Hypertension (continued). "Genomewide association studies (GWAS) have shown ATP2B1, the gene for plasma membrane calcium ATPase 1 (PMCA1), to be highly associated with BP and with essential hypertension, and importantly, demonstrated this as a consistent observation in different ethnic populations." (PMID 28795531, 2017). "In addition, we identified three SNPs in two novel genes (LOC729251 and TCEANC) and seven SNPs in five previously reported genes (FGF5, ATP2B1, CYP17A1, MTHFR and CASZ1) nominally associated with hypertension (Pmeta < 0.05)." (PMID 27480026, 2016). "Moreover, combined analysis of these two datasets further confirmed that only ATP2B1 variants reached genome-wide significance threshold (P < 5 × 10−8) with SBP (rs2681492), DBP (rs2681472), and hypertension (rs2681472)." (PMID 26933664, 2016). "Although dozens of GWASs have been conducted to identify genetic markers for BP traits or hypertension over the past two decades, ATP2B1 may be the first gene that has been cross-validated in different GWASs." (PMID 26933664, 2016). "However, the genetic association between the ATP2B1 or CYP17A1 and hypertension was conflicting." (PMID 34722659, 2021). "In the past 10 years, according to the results of GWAS scans, both ATP2B1 and CYP17A1 have correlation with BP and/or hypertension." (PMID 34722659, 2021). "A total of 178 SNPs were significantly associated with hypertension in GWAS, and 22 SNPs for 21 gene symbols including ATP2B1 and CSK, which were frequently investigated with blood pressure and hypertension, were selected as tagging SNPs." (PMID 28273873, 2017). "Mice lacking Atp2b1 specifically in VSMCs exhibit hypertension, higher intracellular calcium levels and increased sensitivity to nicardipine, a calcium channel blocker." (PMID 34654805, 2021).
breast carcinoma (11 papers, 2016 to 2025). "In comparison with the downregulation of ATP2B1 expression in oral cancer, ATP2B1 expression levels are upregulated in breast cancer." (PMID 35875160, 2022). "In breast cancer cells upregulated ATP2B1, ATP2B2 mRNA and downregulated ATP2B4 mRNA expressions were described previously." (PMID 30352569, 2018). "In which, ATP2B1 upregulation has been reported in tumorigenic breast cancer cell lines previously." (PMID 35031021, 2022). "Although the housekeeping form of ATP2B1 (PMCA1) is stable during development, its expression was changed in oral cancer and breast cancer." (PMID 35875160, 2022). "Prognostic signature and their re-wiring across breast cancer stages were computationally detected and visualized; Amongst, an essential biomarker, AC025034.1, which is the antisense of an oncogene, ATP2B1, was detected." (PMID 35031021, 2022). "Previous in vitro studies showed upregulated ATP2B1 and ATP2B2 mRNA and downregulated ATP2B4 mRNA expression in some breast cancer cell lines." (PMID 30352569, 2018). "Three distinct datasets displayed significantly lower ATP2B4 mRNA expression in invasive breast cancer tissue samples compared to normal breast tissue, whereas the expression of ATP2B1 and ATP2B2 was not altered." (PMID 30352569, 2018). "Interestingly, the absence of ATP2B1 considerably increases the efficacy of ionomycin in breast cancer." (PMID 35875160, 2022). "In contrast, the expression of the ATP2B1 and ATP2B2 genes was not altered in breast cancer tissues." (PMID 30352569, 2018). "Consistent with the IHC data presented above, there were individual breast cancers with relative high levels of PMCA2 (ATP2B2) in all of the molecular subtypes, this was not seen for PMCA1 (ATP2B1) or PMCA4 (ATP2B4)." (PMID 27148852, 2016).